AFP (alpha fetoprotein)
Diseases named in the same sentence as AFP in open-access papers (continued):
Sharing a sentence is not in itself a finding about the gene and the disease.
tumor (continued). "Subgroup analysis was performed according to influencing factors of MVI rate including tumor size, tumor number, BCLC stage, and alpha fetoprotein (AFP) level." (PMID 34804920, 2021). "Alpha-fetoprotein (AFP) and carbohydrate antigen 19-9 (CA19-9) are considered the ideal serum tumor markers for HCC and ICC." (PMID 34804935, 2021). "In the AFP<100 IU/mL group, GGTP terciles showed differences in the tumor characteristics, with significantly more tumor multifocality and percent of patients with PVT in the high CRP group compared to the low CRP group." (PMID 34540270, 2021). "To this end, we first isolated cells from three fresh HCC tumor tissues and confirmed that these cells were primary HCC cells by performing immunostaining of AFP and ASGPR markers." (PMID 34977001, 2021). "Notably, preoperative serum AFP may be an indirect indicator of tumor burden." (PMID 34540664, 2021). "The high PPM1D was related to TNM stage, alpha- fetoprotein (AFP) level, tumor size, recurrence incidence and the family history for HCC." (PMID 34470916, 2021). "GGT was found to be a useful biomarker for prognosis and for tumor aggressiveness parameters, including in patients with small tumors or in HCC patients who have low serum AFP levels." (PMID 34540270, 2021). "Alpha-fetoprotein (AFP) is recognized as a serum marker of HCC and is related to tumor burden in some patients." (PMID 34359658, 2021). "Eventually, six factors were selected, which were the ALBI score, tumor size, the number of invaded liver segments, GGT, AFP, and the PVTT stage." (PMID 33718130, 2021). "The classical features of apoptosis were dose-dependent, appearing for various types of tumor cells, such as Raji, Jurkat and MCF-7 cells, at AFP concentrations of 0.7–3.0 μM and, more significantly, at 5.0–10.0 μM." (PMID 34680245, 2021). "Alpha-fetoprotein (AFP) levels (P = 0.040), tumor size (P = 0.006), satellite nodules (P = 0.024), and microvascular invasion (P<0.001) were significant parameters that correlated with the expression of PRMT4." (PMID 34522186, 2021). "Univariate analysis of prognostic factors of HCC has been the following: Tumor size > 5 cm (P =0.049), BCLC stage (B+C) (P = 0.024), AFP > 400 μg/L (P = 0.002), PIVKA > 400 μg/L (P=0.039), Nanog > 6.7 (P = 0.005), and HBV-DNA > 100 (P=0.017)." (PMID 34123777, 2021). "We confirmed that the key prognostic factors of HCC include current smoking, albumin, prealbumin, AFP, varicose veins of gastric fundus, BDTT, macrovascular invasion, MVI, tumor number, and maximal tumor diameter." (PMID 34976789, 2021). "For RFS, the vascular invasion (P < 0.001), tumor TNM staging (P < 0.001), Serum AFP level (P = 0.029), and high expression of CTSA mRNA (P = 0.003) were risk factors." (PMID 34272452, 2021). "DUSP12-altered patients had a higher serum level of alpha fetoprotein (AFP) at procurement, fraction of genome altered and worse histology grade in neoplasms." (PMID 34414037, 2021). "As summarized, high levels of alpha-fetoprotein (AFP) (>20ng/mL)(p = 0.014), and advanced tumor stage in all grading systems, including UICC (p = 0.01), Edmonson (p = 0.003) and AJCC (p = 0.048), were found to be associated with low expression of TGFβR3." (PMID 33805946, 2021). "To further assess the effect of the cfDNA adsorption rate in the diagnosis of cancer, we compared the cfDNA adsorption rate and serum tumor biomarkers such as CEA, CA19-9 and AFP in the diagnosis of malignant tumors." (PMID 33562269, 2021). "Within the early HCC cohort, the relationships between tumour-related factors and both PIVKA-II and AFP were assessed." (PMID 34853657, 2021).
tumor (continued). "Preoperative blood alpha-fetoprotein (AFP) level, hepatitis B e antigen (HBeAg) status, MVI classification, largest tumor diameter, the status of serosal invasion, number of tumors, and the status of satellite nodules were incorporated to construct a model." (PMID 34229698, 2021). "Despite of the CEA and PSA, other tumor markers including Tumor necrosis factor-alpha (TNF-α), carbohydrate antigen (CA199), and alpha-fetoprotein (AFP) were studied by the biosensing performed on either different material or shaped metasurfaces." (PMID 35009676, 2021). "Alpha-fetoprotein level, macrovascular invasion, MVI, and tumor load have been considered as important prognostic indexes." (PMID 34976789, 2021). "Tumor marker levels, including t-PSA, AFP, CEA, CA125, and CA199, were measured in the clinical laboratory." (PMID 34887933, 2021). "The general importance of T cell mediated anti-tumor effects has also been confirmed by an increasing number of CAR T approaches in HCC, usually targeting glypican 3 or AFP." (PMID 33805268, 2021). "Patients with high FAR had a poorer tumor differentiation (p = 0.004), higher CA19‐9 (p = 0.002), and lower AFP (p = 0.037) compared to those in the low FAR group." (PMID 34105304, 2021). "The performance of CEA, AFP, and CA19-9 and their various combinations was also evaluated for CRC screening to identify the tumor marker combinations with the best performance." (PMID 33977101, 2021). "Using ROC curves, cutoff values for AFP and PIVKAII for HCC detection, tumor grade and microvascular invasion (MVI) were assessed." (PMID 34181327, 2021). "Immuno-PET GTV measurements reliably quantified tumor burden prior to RIT, strongly correlating with serum AFP (R2 = 0.90)." (PMID 33580090, 2021). "After PSM, albumin, INR, AST, AFP, HBV DNA, Edmondson grade, BCLC stage, ALBI score, PLR, NLR, capsule integrity, microvascular invasion, tumour embolus, and tumour size were identified as possible influencing factors in the univariate analysis (P<0.05)." (PMID 34149909, 2021). "Tumor tissues from HCC patients, CCA patients and AFP-GC patients were noted as HCC-PT, CCA-PT and AFP-GC-PT respectively, besides, the normal adult liver tissue was also named as NM-AT." (PMID 34150644, 2021). "It is estimated that serum AFP is significantly elevated in 2/3 HCC patients, which means nearly 1/3 patients have normal AFP level, especially when the tumor is in early stages." (PMID 34650917, 2021). "Patients were transplanted with the following criteria: total tumour volume (TTV) < 115 cm3 and AFP < 400 ng/mL." (PMID 34944957, 2021). "Preoperative predictors of recurrence were tumour burden beyond UCSF criteria, AFP > 100 mg/mL, and FDG-18 PET avidity." (PMID 34944957, 2021). "In contrast, the sensitivities of AFP for stage II, stage III, stage IV, and all CRCs, 5.7%, 8.0%, 3.4%, and 5.7%, respectively, were the lowest among the three tumor markers." (PMID 33977101, 2021). "In line, the expression of two HCC markers, AFP and GP3, was induced in tumor and surrounding liver tissue of both vehicle and GKT771 treated HCC mice." (PMID 33485364, 2021). "Tumor markers showed a slight increase in the CEA and CA 125 markers; however, the Alpha fetus protein (AFP) was at very high levels (AFP = 49800 ng/mL), suggesting the possibility of coexisting gastric neoplasm and primary liver tumor." (PMID 34221269, 2021). "Alpha fetoprotein (AFP), tumor number, tumor size, microvascular invasion (MVI), and differentiation were considered as independent risk factors for RFS in the training cohort, and these were further confirmed in the validation cohort." (PMID 34745962, 2021). "RSF revealed that five parameters, namely size of the tumor, BCLC-B sub-classification, AFP level, ALB level, and number of lesions, were strong predictors of survival." (PMID 33738252, 2021). "The independent sample t-test was used to compare the age, alpha-fetoprotein (AFP) value, tumor size, and tumor enhancement of the two groups." (PMID 34712291, 2021).
tumor (continued). "GAPR combined with GAR and AAR exhibited a larger AUC than single ratio or pairwise combination for distinguishing AFP‐NHCC group with TNMIstage, BCLC stage A, and tumor size less than 3 cm." (PMID 34145988, 2021). "Patients fell into 12 subgroups for survival analysis according to their clinical characteristics such as AFP levels, vascular invasion, histological grade, AJCC TNM stage, new tumour after initial treatment and individual tumour status." (PMID 33300278, 2021). "It is worth nothing that Milan criteria, TNM stage, tumor size, microvascular invasion, pre-OLT serum AFP level, and recipient rs9292795 (TT vs. AA/AT) were considered to be statistically significant factors for both RFS and OS (P < 0.05)." (PMID 33964921, 2021). "Alpha-fetoprotein (AFP) is another glycoprotein that is overexpressed by HCC tumor cells and is well-known as a tumor biomarker in HCC." (PMID 33946408, 2021). "Higher serum concentrations of AFP and VEGF-A, lower lymphocyte count, peritumoral enhancement, irregular tumor shape, and intratumoral artery are promising markers for MVI prediction in HCC." (PMID 35004273, 2021). "According to analysis of tumor markers, CEA, CA19-9, CA72-4, and AFP showed different degrees of decline, of which CEA was the most sensitive (where 75% of patients had a decline)." (PMID 34336697, 2021). "Peritumoral mammary adipocytes as well as fibroblasts and lymphocytes infiltrating the tumor, which expressed AFPR, were detected in the activation of the AFP gene and expression of the AFP mRNA transcripts." (PMID 34680245, 2021). "The majority of cases reported the elevations in AFP concentration in patients with HAS, and the serum AFP concentration was associated with HAC cell component percentage: the higher HAC cell component ratio in a tumor, the more AFP could be secreted by the tumor." (PMID 33912455, 2021). "As for tumor markers, six patients showed increased serum CA19-9, two showed increased serum CA125, and only one showed increased serum AFP in patients with IgG4-AIC." (PMID 33816216, 2021). "Rates of tumor-related symptoms (ECOG performance status of 1) and serum AFP ≥ 400 ng/mL were higher in tumors of larger size." (PMID 34440584, 2021). "We also compared the cfDNA adsorption rate and tumor biomarkers such as CEA, AFP and CA19-9 in the diagnosis of CRC, LC, HCC and other malignant tumors." (PMID 33562269, 2021). "These analyses also indicated that RFS was significantly related to albumin <3.5 g/dL, ChE <250 IU/L, ICGR15 ≥15%, AFP ≥20 ng/mL, PIVKA‐II ≥100 mAU/mL, RHBPP ≥1.036, and tumor size ≥5 cm, except in cases of the simple nodular type." (PMID 33490612, 2021). "Alpha-fetoprotein (AFP) and beta-human chorionic gonadotropin (β-HCG) can be elevated with any entity of tumor." (PMID 33996471, 2021). "When detecting disease, AFP, beta-HCG and LDH are currently the only clinically suitable serum tumour markers." (PMID 34298776, 2021). "We also provide data on tumor biology, such as AFP and PIVKA-II values throughout the treatment period and other specific data on tumor pathology." (PMID 34733878, 2021). "AFP is a known predictor of OS in various clinical situations of HCC patients and characteristics of the tumor." (PMID 33294952, 2021). "When compared to the tumor marker data, the most striking observation was that the sensitivities of mSDC2 and mSEPT9+mSDC2 for AA and SP detection were much higher than those of even the best tumor marker combinations, CEA+CA19-9 and CEA+AFP+CA19-9." (PMID 33977101, 2021). "Surprisingly, AFP, MVI, differentiation, tumor size, and tumor number were found to be significant independent risk values for RFS in the validation cohort." (PMID 34745962, 2021). "As previously reported, HCC patients with high levels of both AFP and DCP tumor markers are assumed to have a poor prognosis." (PMID 33562238, 2021).
tumor (continued). "Nowadays, genetic modification with T-cell receptors (TCRs) specific for AFP can potentially redirect TCR-gene-engineered human T cells to specifically recognize and then kill HCC tumor cells." (PMID 34680245, 2021). "The tumor marker test revealed a high protein induced by vitamin K absence or antagonist-II (PIVKA-II) level of 181 mAU/ml and a normal alpha-fetoprotein (AFP) of 7 ng/ml." (PMID 33665746, 2021). "Exosomes, derived from AFP‐expressing DCs (DEXAFP) in mouse models, revealed an efficient triggering of antigen‐specific immune responses, substantial tumour growth retardation and increased survival rates." (PMID 34423899, 2021). "Based on VIMP, we identified and evaluated five parameters, namely tumor size, BCLC-B sub-classification, AFP, and ALB levels, as well as number of lesions as strong predictors." (PMID 33738252, 2021). "Other laboratory tests, including those for tumor markers carbohydrate antigen 199 (CA199), carbohydrate antigen 125 (CA125), carcinoembryonic antigen (CEA), and alpha fetoprotein (AFP), were normal." (PMID 33466160, 2021). "From this point of view, AFP seemed to contribute to ATRA induced cell death, which was obviously against its well-known tumor promoting function." (PMID 33495541, 2021). "Before PSM, albumin, INR, AST, ALT, AFP, HBV DNA, Edmondson grade, BCLC stage, ALBI score, PLR, NLR, capsule integrity, microvascular invasion, tumour embolus, tumour size, and SM were the possible influencing factors in the univariate analysis (P<0.05)." (PMID 34149909, 2021). "Previous studies have noted that preoperative serum alpha-fetoprotein (AFP) levels and various histological features of tumors such as tumor size and microvascular invasion are independent predictors of recurrence after resection." (PMID 34885252, 2021). "The results indicated BIS levels were significantly higher in patients with AFP positive values, grade III/IV, MVI, and tumor size ≥5 cm (p < 0.001)." (PMID 35004275, 2021). "Our results showed consistency with other reports and AFP and PIVKAII were both significantly elevated in patients with larger tumors, more tumor nodules and macrovascular invasion." (PMID 34181327, 2021). "They suggested tumor screening for all BWS patients with both abdominal ultrasound and AFP dosage every three months until four years of age and renal ultrasound every three months until seven years of age." (PMID 33810554, 2021). "AFP and DCP are a wide range of tumor markers closely related to HCC, which are often used in the diagnosis of HCC and the prognosis of tumor recurrence." (PMID 33859298, 2021). "ICS with a short-term T cell line showed that the AFP-specific T cell response was predominantly restricted by CD8+ T cells, which, as responsive T cells, is a signature of malignant tumour status." (PMID 34496797, 2021). "As for the OS, the C-index of the nomogram was 0.716, which was statistically higher than the PLR (0.559), aspartate aminotransferase (0.591), AFP (0.584), tumor encapsulation (0.591), HBV-DNA (0.569) and tumor diameter (0.635) (all P < 0.001)." (PMID 33178607, 2020). "In this study, we first profiled site-specific glycans from low and high AFP levels of HCC tumors and non-tumor tissues." (PMID 32426269, 2020). "Tumor makers of carbohydrate antigen 19–9 (CA199), carcinoembryonic antigen (CEA), alpha-fetoprotein (AFP) were within the normal limits." (PMID 32938404, 2020). "This score includes parameters for liver function (1 point each for albumin < 36 g/dl or bilirubin > 17 μmol/l) and tumour burden (1 point each for alpha-fetoprotein (AFP) > 400 ng/ml and tumour size > 7 cm)." (PMID 32125515, 2020). "Oncopig HCC cell lines produced alpha fetoprotein (AFP) at similar levels as HepG2 cells, demonstrating the potential utility of serum AFP as a biomarker for tumor growth in the Oncopig HCC model, similar to clinical practice." (PMID 32733642, 2020).
tumor (continued). "The patients with PBT had larger tumor burden (i.e., large tumors, multiple tumors, incomplete tumor capsules, PVTT, MVI, high levels of AFP) and higher level of inflammatory indexes (NLR, PLR and APRI) compared with those with non-PBT." (PMID 32471389, 2020). "The serum levels of AFP and PIVKA-II were positively correlated with tumor differentiation and size." (PMID 33292429, 2020). "After radiation, the patient reported a significant improvement in pain symptoms and alpha-fetoprotein (AFP) levels, a tumor marker for HCC (normal range: < 20 ng/L), quickly returned to normal." (PMID 31914098, 2020). "Very few circulating markers are currently used for the diagnosis of chronic liver diseases and HCC, among which, alpha-fetoprotein (AFP) is frequently used in clinics for HCC diagnosis and for evaluating tumor recurrence." (PMID 32932781, 2020). "In preoperative factors, multivariable analyses of that were prognostically significant, and the univariable analysis showed that the LSG, ICGR15, AFP, PIVKA2, and tumor size were significant." (PMID 33272298, 2020). "An increase was also recorded in the following tumor markers: carbohydrate antigen (CA) -125 in 3 (10.7%), beta-human chorionic gonadotropin (β-HCG) in 6 (21.4%), alpha-fetoprotein (AFP) in 11 (39%), CA 19.9 in 2 (7%), and CA-15.3 in 1 patient (3%)." (PMID 32991408, 2020). "AFP, HCG and LDH are important tumor markers that are helpful in diagnosis, staging and evaluation of response to the therapy." (PMID 31851466, 2020). "AFP, AST, MRI-reported tumour number, MRI-reported tumour size and BCLC stage were found to be significantly different between groups." (PMID 31937925, 2020). "Six patients underwent tumor marker examination during follow-up period and the positive rate were as followed: CA-125 83.3% (5/6), CA-199 16.7% (1/6), CEA 0.0% (0/6), AFP 0.0% (0/6)." (PMID 32899024, 2020). "Serum AFP is a widely used tumor marker of HCC, and the positive serum AFP (>20 ng/ml) is seen in approximately 19% of ICC patients." (PMID 33552957, 2020). "The levels of tumor markers (CA19-9, CEA, and AFP) and a liver function test were also used to monitor CCA patients after treatment." (PMID 32039729, 2020). "Compared with the traditional 2D cultured tumor cells (2D-HepG2), 3DP-HepG2 showed significantly improved expression of tumor-related genes, including ALB, AFP, CD133, IL-8, EpCAM, CD24, and β-TGF genes." (PMID 32582546, 2020). "At the same time, when studying the relationship between AFP, PIVKA-II level and tumor size, all the selected HCC cases were all single tumors and multiple tumors were excluded by imaging examinations." (PMID 33292429, 2020). "There is a strong correlation between levels of HMGB1 evaluated by Western blot analysis and the clinical and pathological features of HCC, including correlations with serum alpha-fetoprotein (AFP) levels and tumor size." (PMID 32664328, 2020). "Thirteen seminomatous and 13 non-seminomatous, a total of 26 patients with localized TGCT had preoperative increased serum tumor markers (elevated HCG and/or AFP and/or LDH) which normalized after orchiectomy." (PMID 31851466, 2020). "For the tumor characteristics, patients in the Pre‐SVR group had significantly lower level of AFP (P = .002)." (PMID 33319162, 2020). "Variables including E2F8, gender, body mass index, race, tumor status, family history of cancer, pathological grade, AJCC stage, vascular invasion, AFP, new tumor event after initial treatment and hepatic inflammation were included in the univariate analysis." (PMID 31990034, 2020). "According to the univariate analysis, HBsAg, HBV-DNA, AFP, NLR, PLR, largest tumor size, hemorrhage, intraoperative transfusion, differentiation, MVI, capsule and Rad-score were potential risk factors for OS." (PMID 33198809, 2020). "PMGCTs share the same serum tumor markers (STMs) with gonadal GCTs, such as lactate dehydrogenase (LDH), alpha-fetoprotein (AFP), and beta-human chorionic gonadotropin (β-HCG)." (PMID 32766147, 2020).